CDKN1A (cyclin dependent kinase inhibitor 1A)
Diseases named in the same sentence as CDKN1A in open-access papers (continued):
Sharing a sentence is not in itself a finding about the gene and the disease.
COVID-19 (7 papers, 2022 to 2024). A disease caused by infection with severe acute respiratory syndrome coronavirus 2. "Other genes commonly associated with COVID-19 immune responses (e.g., Stat1, Myd88, Il1b Nlrp3, Cdkn1a, and Casp1) were also upregulated in responder brains." (PMID 36739463, 2023). "CDKN1A is markedly upregulated in COVID-19 dependent muscle loss." (PMID 37638007, 2023). "The ‘dark’ gene CDKN1A is one of the targets associated with cell proliferation and cell cycle, and is also the promising target on which berberine may act to regulate immune responses, inflammatory processes, and cell activities against COVID-19 and SARS infection." (PMID 37853311, 2023). "In particular, a study showing COVID-19–specific transcriptomic signatures included Cdkn1a." (PMID 38775156, 2024). "Expression of the senescence markers CDKN1A is significantly increased in epithelial ciliated and club cells from patients with severe COVID-19 compared with those with moderate disease and with healthy control subjects, suggesting that lung cell senescence induction coincided with virus detection." (PMID 37853311, 2023). "Thus, more future studies are needed to fully understand the role of CDKN1A as well as other hub genes in both COVID-19 and HFRS." (PMID 37234545, 2023). "In COVID-19, studies have reported that CDKN1A is upregulated in the lung tissue of infected patients, which could lead to the inhibition of virus replication and decreased inflammation in the host." (PMID 37234545, 2023). "Many of the cell cycle-related genes, such as aurora kinase B (AURKB) and cyclin-dependent kinase inhibitor 1A (CDKN1A, p21), were consistently upregulated in a COVID-19 specific manner, while some were consistently downregulated, such as cyclin-dependent kinase inhibitor 1C (CDKN1C, p57)." (PMID 35991542, 2022). "For instance, CDKN1A has been observed to have significantly higher expression in COVID-19 patients than in healthy controls, which is in agreement with our results of COVID-19 specific CDKN1A upregulation." (PMID 35991542, 2022). "The protein–protein interaction (PPI) network of DEGs was then constructed and six genes named RAD51, ALDH1A1, UBA52, CUL3, GADD45B, and CDKN1A were identified as the commonly dysregulated hub genes among HFRS and COVID-19." (PMID 37234545, 2023). "Our study uncovered six genes named RAD51, ALDH1A1, UBA52, CUL3, GADD45B, and CDKN1A were found to be commonly dysregulated among HFRS and COVID-19." (PMID 37234545, 2023). "Subsequently, three key genes (CDKN1A, IFI27, and STAB1) were screened using machine learning to predict the occurrence of COVID-19 related IIM." (PMID 37638007, 2023). "We found that both infected and bystander (not infected) BALF epithelial cells of severe COVID-19 patients presented upregulation of mTOR signaling genes, including SQSTM1 and CDKN1A." (PMID 36661509, 2022).
HIV-1 infection (7 papers, 2008 to 2021). The type species of lentivirus and the etiologic agent of acquired immunodeficiency syndrome (AIDS). "Future studies of the susceptibility of PBMC of HIC to HIV-1 infection in vitro should analyze the potential role of both CDKN1A/p21 and ZC3H12A/MCPIP1 simultaneously." (PMID 32615986, 2020). "Moreover, a second mechanism related with CDKN1A has been associated with EC phenotype, describing a partial resistance of CD4+ T cells from these individuals to HIV-1 infection mediated by a strong and selective upregulation of CDKN1A, also called p2124." (PMID 31582776, 2019). "Increased expression of CDKN1A/p21 and ZC3H12A/MCPIP1 associated with T cell and/or monocyte activation may be a distinctive homoeostatic response to limit the deleterious effects of aberrant chronic immune activation and inflammation-driven by HIV-1 infection." (PMID 32615986, 2020).
Hyperglycemia (7 papers, 2011 to 2024). An increased concentration of glucose in the blood. "Hyperglycemia enhances DNA damage in MSCs; hence, we assessed the expression of DNA repair markers XRCC5, TERF1, CDKN1A, and SIRT1 in ASCs in a diabetic milieu." (PMID 38880916, 2024). "In HEC-1A cells, metformin-induced favorable CDKN1A upregulation occurred only during normoglycemia, but not hyperglycemia, which was in contrast to CDKN1A transcript regulation." (PMID 37313172, 2023). "However, we did not observe any Cdkn1a or Mmp2 expression in Gcg+ islet cells in non-infiltrated/intact islets of 8-week mice, insulitic islets in 13-19-week old euglycemic NOD mice, or in residual islets of recently diabetic (<1 week after hyperglycemia) 19-20 week NOD mice (n = 3 mice per group)." (PMID 36277717, 2022).
idiopathic pulmonary fibrosis (7 papers, 2010 to 2025). Idiopathic pulmonary fibrosis (IPF) is a nonneoplastic pulmonary disease that is characterized by the formation of scar tissue within the lungs in the absence of any known cause. "In addition to elevated expressions of CDKN1A in fibrotic tissues, genetic variants of CDKN1A have also been identified as associated with a greater risk of suffering from idiopathic pulmonary fibrosis." (PMID 37569323, 2023). "It is interesting to note that CDKN1A is associated with POAG and also with certain fibrotic conditions such as idiopathic pulmonary fibrosis." (PMID 38990974, 2024). "Also, FPNI treatment prevented the upregulation of senescence markers that are well-known to be associated to lung fibrosis, such as TNF-α, Il6, Cdkn1a and Cdkn1b along with that of collagen isoforms Col1a1 and Col3a1." (PMID 38167804, 2024).
liver fibrosis (7 papers, 2014 to 2025). "This indicates that CDKN1A is a promising target for restoring endothelial function in the regression of liver fibrosis and should be considered when developing new drugs to treat the disease in the future." (PMID 40006040, 2025). "The authors further found that the genetic inactivation of CDKN1A in mice led to the clearance of senescent hepatic stellate cells, which was accompanied by a significant reduction in liver fibrosis and collagen production." (PMID 40133262, 2025). "The in vitro and in vivo data collectively suggest that EZH2 and JMJD3 coordinately modulate HSCs activation and liver fibrosis through, at least in part, epigenetically regulating Bambi, Cdkn1a, Gadd45a and Gadd45b." (PMID 33391480, 2021). "The univariate logistic regression analysis indicates that the three hub genes affect the occurrence of liver fibrosis, as follows: CDKN1A with an odds ratio (OR) of 1.22 (95% CI: 1.08–1.39), NR1I3 with an OR of 0.92 (95% CI: 0.87–0.89), and TUBB1 with an OR of 0.95 (95% CI: 0.80–1.16)." (PMID 40006040, 2025). "The therapeutic effects of DZNep as epigenetic drug in liver fibrosis are associated with the regulation of EZH2 towards direct target genes encoding TGF-β1 pseudoreceptor BAMBI, anti-inflammatory cytokine IL10 and cell cycle regulators CDKN1A, GADD45A and GADD45B, which are also regulated by JMJD3." (PMID 33391480, 2021).
osteoarthritis (7 papers, 2019 to 2025). A noninflammatory degenerative joint disease occurring chiefly in older persons, characterized by degeneration of the articular cartilage, hypertrophy of bone at the margins and changes in the synovial membrane. "For example, EV-delivered miR-34a-5p (miR-34a), which targets the cyclin-dependent kinase inhibitor 1A (p21Cip1/Waf1), was implicated as a mechanism by which senescent chondrocytes from osteoarthritis patients induce senescence in nearby chondrocytes." (PMID 38132089, 2023). "Meanwhile, we found that cyclin‐dependent kinase inhibitor 1A (CDKN1A) was less studied in osteoarthritis." (PMID 30560591, 2019). "The classification model constructed by LASSO analysis showed that six genes including CDKN1A, FOSB, STMN2, SLC2A3, TAC, and SCRG1 can be used as biomarkers of osteoarthritis, and the SCRG1 gene shows importance in osteoarthritis." (PMID 35720295, 2022).
sarcopenia (7 papers, 2021 to 2025). Progressive decline in muscle mass due to aging which results in decreased functional capacity of muscles. "Specifically, in the sarcopenia dataset, the CEBPB showed the best diagnostic efficiency for differentiating sarcopenia, while BTG2, CDKN1A, CEBPB, DDIT4, and NFKBIA showed the best-differentiating capability in the OA dataset." (PMID 38962732, 2024). "Among them, MYH8, HOXB2, C1QA, CDKN1A, and SLC38A1 are associated with sarcopenia, and in this study, LGR5, SERPINA5, and TPPP3 genes were found to be associated with Sarcopenia for the first time." (PMID 38229116, 2024). "In the sarcopenia samples, pathways such as type 2 papillary renal cell carcinoma, EPO-NF-κb pathway, and RUNX3 regulates CDKN1A transcription were significantly enriched." (PMID 41463417, 2025). "In patients with sarcopenia, the expression of TPPP3, C1QA, LGR5, MYH8, and CDKN1A genes are upregulated, and the expression of SLC38A1, SERPINA5, and HOXB2 genes are downregulated." (PMID 38229116, 2024). "In the sarcopenia dataset, BTG2 (AUC = 0.867), CDKN1A (AUC = 0.892), CEBPB (AUC = 0.942), DDIT4 (AUC = 0.792), FOXO3 (AUC = 0.900), NFKBIA (AUC = 0.892), ZBTB16 (AUC = 0.808) and ZFP36 (AUC = 0.775) demonstrated better diagnostic efficacy in distinguishing sarcopenia patients from healthy controls." (PMID 38962732, 2024).
Stroke (7 papers, 2013 to 2025). Sudden impairment of blood flow to a part of the brain due to occlusion or rupture of an artery to the brain. "In addition to CDKN1A, which has been previously reported to be associated with IS, miR-17-5p and miR-20a-5p have been identified as promising candidate biomarkers for distinguishing embolic stroke from thrombotic stroke." (PMID 37323662, 2023). "High expression of the CDKN1A gene was found in microglia nodules compared to stroke nodules in donors’ brain tissue post mortem." (PMID 40507797, 2025). "Both Gadd45a and Cdkn1a were significantly upregulated in post-stroke muscle." (PMID 32629989, 2020). "In addition, genome-wide association studies (GWAS) have associated variants in VEGFA with coronary heart disease and myocardial infarction, and variants in other gene targets of miR-20a-5p, CDKN1A (also a common gene target of miR-181a-5p) and PRKG1 with stroke." (PMID 36613546, 2022). "In this study, four biomarkers, CDKN1A, GPX4, PRDX1, and PRDX6, were used to diagnose stroke and assess the treatment effects." (PMID 38360841, 2024). "RT–qPCR and Western blot methods confirmed significant changes in the expression levels of Aplnr, Cdkn1a, Irak2, and Serpine1 after MCAO, which may serve as therapeutic targets to prevent cardiovascular complications after stroke." (PMID 37965346, 2023).
triple-negative breast carcinoma (7 papers, 2012 to 2026). An invasive breast carcinoma which is negative for expression of estrogen receptor (ER), progesterone receptor (PR), and human epidermal growth factor receptor 2 (HER2). "CDKN1A/p21 downregulation is suggested to be necessary for Plasmacytoma Variant Translocation 1 (PVT1) lncRNA-induced EMT in triple-negative breast cancer cells and in pancreatic cancer cells." (PMID 38139316, 2023). "By combining the PARP inhibitor (PARPi), talazoparib, with radiation, senescence was enhanced in 4T1 and MDA-MB-231 triple-negative breast cancer cell lines (based on SA-β-gal upregulation, increased expression of CDKN1A and the senescence-associated secretory phenotype (SASP) marker, IL6)." (PMID 38002066, 2023). "In a previous investigation we demonstrated that the I3C derivative CTet is able to induce autophagy, and to inhibit cell proliferation in estrogen receptor-positive and triple negative breast cancer cell lines through p21/CDKN1A and GADD45A overexpression." (PMID 22905241, 2012). "To verify that the taRNA-mediated upregulation of protein levels can produce a phenotypic effect, we used PTV-IIIab-based taRNAs to simultaneously boost the expression of both PTEN and CDKN1A in the triple-negative breast cancer cell line, MDA-MB-231, and monitored cellular viability." (PMID 37884512, 2023).
cholangiocarcinoma (6 papers, 2018 to 2022). A carcinoma that arises from the intrahepatic biliary tree (intrahepatic cholangiocarcinoma) or from the junction, or adjacent to the junction, of the right and left hepatic ducts (hilar cholangiocarcinoma). "Upregulated SNHG1 could promote cholangiocarcinoma cell proliferation, migration, and cell cycle but reduce apoptosis, and the interaction between SNHG1 and EZH2 could target CDKN1A to promote the biological behavior of cholangiocarcinoma." (PMID 31691514, 2019). "By regulating the transcription of CDKN1A epigenetically in the nucleus, lncRNA SNHG1 is likely to promote malignancy of cholangiocarcinoma." (PMID 32851072, 2020).
chronic myelogenous leukemia (6 papers, 2013 to 2024). "From previous studies, expression of DNMT1 and CDKN1A showed a negative regulation mechanism on chronic myelogenous leukemia." (PMID 33133123, 2020). "High levels of miR-17-5p, which further downregulate CDKN1A (Cyclin Dependent Kinase Inhibitor 1A), p21 and E2F1 tumor suppressor genes in imatinib sensitive and resistant chronic myeloid leukemia (CML) cells compared to peripheral blood mononuclear cells (PBMCs), have also been observed." (PMID 29050357, 2017).
fibrosarcoma (6 papers, 2017 to 2025). A malignant mesenchymal fibroblastic neoplasm affecting the soft tissue and bone.
head and neck cancer (6 papers, 2009 to 2023). A primary or metastatic malignant neoplasm affecting the head and neck. "Overall, an up-regulation of PHPT1, CCNG1, CDKN1A, GADD45, and SESN1 was found in endometrial and head and neck cancer patients at all time points with the exception of SESN1." (PMID 29474504, 2018). "Hence, PHPT1 and CDKN1A were significantly up-regulated at all time points in endometrial patients (respectively) while a significant up-regulation in head and neck cancer patients was observed for PHPT1 and CDKN1A only at 48 hr, after the 2nd RT fraction (respectively)." (PMID 29474504, 2018).
head and neck squamous cell carcinoma (6 papers, 2017 to 2025). A squamous cell carcinoma that arises from any of the following anatomic sites: lip and oral cavity, nasal cavity, paranasal sinuses, pharynx, larynx, and salivary glands. "CDKN1A rs1059234 polymorphism was found to be associated with increased risk of head and neck squamous cell carcinoma (HNSCC)." (PMID 28445979, 2017).
Hepatitis B (6 papers, 2007 to 2024).
kidney cancer (6 papers, 2014 to 2023). Primary or metastatic malignant neoplasm involving the kidney. "HNF4A is known to control cell proliferation in kidney cancer cell lines, and regulates a number of well-known cancer-associated genes to do so (e.g. CDKN1A and TGFA)." (PMID 25961905, 2015). "For instance, HIF1A binds to MAX and disrupts MYC/MAX complexes, leading to reduced cyclin D2 expression, induction of p21 (CDKN1A), and G1 phase cell cycle arrest in human pVHL-null kidney cancer cell lines." (PMID 37998757, 2023).
retinoblastoma (6 papers, 2014 to 2024). A malignant tumor that originates in the nuclear layer of the retina. "For instance, the GWAS studies on retinoblastoma show that it is caused by MDM2 and CDKN1A mutations in addition to RB1 mutation." (PMID 38540335, 2024). "As for CCND1 and CDKN1A, 3′ untranslated regions (UTRs) of both genes have sequences aligned with some of miR-17-92 clusters which is elevated in retinoblastoma." (PMID 25359779, 2014). "In retinoblastoma ARPE-19, HRMECs, Y79 cells, and the silencing of STAT3 by siRNA reduced cell proliferation and the expression of STAT3-related genes, such as BCL2, BCL2L1, BIRC5, MMP9, VEGFA, CCND1, cyclin-dependent kinase inhibitor 1A (CDKN1A), and MYC." (PMID 38067351, 2023).
rhabdomyosarcoma (6 papers, 2014 to 2025). A rare aggressive malignant mesenchymal neoplasm arising from skeletal muscle. "Similar effects have been reported for SAHA, which downregulates cyclin D1 and upregulates CDKN1A and CDKN1B in rhabdomyosarcoma models, indicating that HDACi broadly regulate cell cycle-associated genes." (PMID 40671124, 2025). "Foxf1 depletion in rhabdomyosarcoma cells increased levels of the CDK inhibitor Cdkn1a (P21Cip1), whereas Foxf1-overexpression reduced Cdkn1a levels." (PMID 28878348, 2017).
acute lymphoblastic leukemia (5 papers, 2013 to 2022). Leukemia with an acute onset, characterized by the presence of lymphoblasts in the bone marrow and the peripheral blood. "Matrine can inhibit the expression of hsa-mir-106 b-3p and upregulate the expression of CDKN1A in human acute lymphoblastic leukemia (ALL) cell line CCRF-CEM, thereby blocking the cell cycle at G0/G1 phase and inducing apoptosis." (PMID 32477114, 2020). "Studies of the methylation status of the CDKN1A promoter in bone marrow cells in 124 patients with acute lymphoblastic leukaemia showed hypermethylation in 41% (51 of 124) of these patients." (PMID 23658227, 2013). "CDKN1A may dominate the drug responsiveness of acute lymphoblastic leukemia (ALL) cells." (PMID 34354942, 2021). "Additionally, a study of acute lymphocytic leukemia patients that received six fractions of 2 Gy TBI showed a significant and sustained increase in blood-based Cdkn1a after each fraction." (PMID 34364390, 2021).
coronary heart disease (5 papers, 2016 to 2025). "Studies have indicated that CDKN1A may promote coronary heart disease by promoting chronic inflammation and sustained inflammatory states." (PMID 39512814, 2024). "Other smoking-related hub genes found to overlap with coronary heart disease-related expression profile include NEDD4L, BCL2L1 and CDKN1A." (PMID 26837704, 2016).